ZC3H4 (zinc finger CCCH-type containing 4)
Description:
RNA-binding protein that suppresses transcription of long non-coding RNAs (lncRNAs). LncRNAs are defined as transcripts more than 200 nucleotides that are not translated into protein. Together with WDR82, part of a transcription termination checkpoint that promotes transcription termination of lncRNAs and their subsequent degradation by the exosome. The transcription termination checkpoint is activated by the inefficiently spliced first exon of lncRNAs.
Synonyms: C19orf7; KIAA1064
Tractability: PROTAC: ubiquitination databases record sites on it; its protein half-life has been measured.
Gene: Protein-coding gene on chromosome 19 (47,064,187 to 47,113,776, reverse strand). Ensembl gene ENSG00000130749.
Subcellular location: Chromosome
Subcellular location (Human Protein Atlas): Nucleoplasm; Cytosol
Pathways (Reactome):
Metabolism of RNA: Nuclear RNA decay
Gene Ontology:
Molecular function: promoter-specific chromatin binding; protein binding; RNA binding; DNA-binding transcription repressor activity, RNA polymerase II-specific; chromatin binding; metal ion binding
Biological process: lncRNA catabolic process; negative regulation of DNA-templated transcription, elongation; negative regulation of lncRNA transcription; nuclear RNA surveillance; negative regulation of DNA-templated transcription; negative regulation of transcription by RNA polymerase II
Cellular component: chromosome; cytosol; nucleoplasm
Genetic constraint (gnomAD): Loss-of-function variants: 10 observed, 94.42 expected, observed/expected ratio (o/e) 0.11, 90% interval 0.064 to 0.18. The synonymous counts are far from expectation, so gnomAD's model fits this gene poorly and the ratio says little. Missense variants: 1,605 observed, 1,649.6 expected, observed/expected ratio (o/e) 0.97, 90% interval 0.93 to 1.01. Synonymous variants: 843 observed, 675.31 expected, observed/expected ratio (o/e) 1.25, 90% interval 1.18 to 1.32.
Homologues: Orthologues: chimpanzee ZC3H4 (99% identical), dog ZC3H4 (94% identical), macaque ZC3H4 (92% identical), mouse Zc3h4 (92% identical), rat Zc3h4 (91% identical), rabbit ZC3H4 (88% identical), guinea pig ZC3H4 (81% identical), pig ZC3H4 (80% identical), tropical clawed frog zc3h4 (60% identical), zebrafish zc3h4 (55% identical). Paralogues in human: ZC3H6 (33% identical), ZC3H8 (8% identical).
Diseases named in the same sentence as ZC3H4 in open-access papers:
ZC3H4 is named in the same sentence as 6 diseases in open-access papers, as found by Europe PMC text mining. Sharing a sentence is not in itself a finding about the gene and the disease. The quoted sentences say what the papers report.
silicosis (5 papers, 2019 to 2024). Silicosis is a respiratory disease caused by breathing in (inhaling) silica dust. "Additionally, ZC3H4 is a crucial protein associated with silicosis that can regulate IL-10 release by controlling autophagy in monocytes." (PMID 35962397, 2022). "ZC3H4 protein upregulation is revealed in tissues of silicosis patients, exhibiting the feasibility of ZC3H4 as the candidate therapeutic target for silicosis." (PMID 39239069, 2024). "Interestingly, circZC3H4, which is transcribed from ZC3H4, plays a similar role to circHECTD1 in silicosis, possibly because ZC3H4 and ZC3H12A belong to the family of CCCH‐typezinc finger proteins." (PMID 33533071, 2021). "Importantly, increased levels of the ZC3H4 protein have been confirmed in tissue samples from patients with silicosis, suggesting that ZC3H4 may be a potential therapeutic target for silicosis." (PMID 30611252, 2019).
pulmonary fibrosis (4 papers, 2021 to 2025). Chronic progressive interstitial lung disorder characterized by the replacement of the lung tissue by connective tissue, leading to progressive dyspnea, respiratory failure, or right heart failure. "We also investigated prosurvival signals to further explore the molecular mechanism underlying the increase in ZC3H4 expression since these pathways were shown to have an important role in anoikis and pulmonary fibrosis." (PMID 35216634, 2022). "In this study, ZC3H4 was observed to regulate the anoikis resistance of fibroblasts and participate in pulmonary fibrosis." (PMID 35216634, 2022). "Accordingly, both ZC3H12A and ZC3H4 are involved in the progression of pulmonary fibrosis, but the connection to anoikis is still unclear." (PMID 35216634, 2022). "In the current study, the zinc finger protein ZC3H4 was shown to promote anoikis resistance in fibroblasts and subsequently induce pulmonary fibrosis." (PMID 35216634, 2022). "The PI3K and MAPK signaling pathways are activated during pulmonary fibrosis, and anoikis resistance is regulated by ZC3H4." (PMID 35216634, 2022). "At the molecular level, the zinc finger protein ZC3H4 has emerged as an important monocyte regulator capable of attenuating pulmonary fibrosis progression through interleukin-10 (IL-10)-mediated anti-inflammatory mechanisms, highlighting potential molecular targets for therapeutic intervention." (PMID 40650314, 2025). "In this study, we found that ZC3H4 could regulate the autophagy pathway to inhibit IL-10 release in monocytes, indicating the complicated and key role of ZC3H4 in pulmonary fibrosis." (PMID 35962397, 2022). "We assessed the expression of ZC3H4, a member of the zinc finger protein family, in fibroblasts to obtain a better understanding of the molecular mechanism of anoikis resistance, since ZC3H4 was shown to be involved in pulmonary fibrosis." (PMID 35216634, 2022). "This study revealed that ZC3H4 regulated the secretion function of monocytes, which, in turn, inhibited fibroblast function in early inflammation through autophagy signaling, thereby reducing pulmonary fibrosis." (PMID 35962397, 2022). "During the formation of pulmonary fibrosis, ELK1 transcriptionally regulates the expression of ZC3H4 to promote the silica-induced EMT program." (PMID 34970415, 2021). "In addition, the ZC3H4 signaling pathway was verified, in which MAPK/PI3K signaling promoted anoikis resistance, followed by pulmonary fibrosis." (PMID 35216634, 2022).
diabetes (1 paper, 2020). "In our analysis, both MR + COLOC and MR + eCAVIAR have consistently shown evidence for causal effects on diabetes mediated by BMI for four genes (TFAP2B, TCF7L2, FTO and ZC3H4)." (PMID 32366963, 2020). "Both of the approaches (MR + COLOC and MR + eCAVIAR) have highlighted shared causal SNPs of BMI and diabetes for four genes (TFAP2B, TCF7L2, FTO and ZC3H4)." (PMID 32366963, 2020).
Obesity (1 paper, 2023). Accumulation of substantial excess body fat. "It is also important to note that the novel EC proteins, APP, CAD, BRD2 (which is part of DKFZp313H139), CST3, GRN, PPM1G and ZC3H4, have all been reported to be positively associated with obesity or adiposity, whilst the novel EC protein SLC25A24 may even prevent obesity and promote leanness." (PMID 37760635, 2023).
ZC3H4 also shares sentences with these, for which no sentence is quoted: asthma (1 paper); tumor (1).